RNASEL (ribonuclease L)
Diseases named in the same sentence as RNASEL in open-access papers (continued):
Sharing a sentence is not in itself a finding about the gene and the disease.
Stroke (1 paper, 2024). Sudden impairment of blood flow to a part of the brain due to occlusion or rupture of an artery to the brain. "It has been reported that RNASEL plays an important role in the development of stroke, and RNASE also has the functions of regulating the cell cycle and apoptosis." (PMID 39290696, 2024). "ELISA detected the expression of C1QBP, RPS28 and RNASEL proteins in stroke patients, and the proportion of neutrophils was significantly increased in the high-risk group." (PMID 39290696, 2024).
tuberculosis (1 paper, 2025). A chronic, recurrent infection caused by the bacterium Mycobacterium tuberculosis. "The discovery of these six mRNAs (NEDD4, PLTP, RNASEL, SEMA7A, TAPBP, and THBS1) not only reveals critical molecular mechanisms underlying immune regulation in tuberculosis but also establishes a robust theoretical foundation for advancing diagnostic and therapeutic strategies." (PMID 40182927, 2025). "NEDD4, PLTP, RNASEL, SEMA7A, TAPBP, and THBS1 were combined into a 6-mRNA feature panel for diagnosis of tuberculosis." (PMID 40182927, 2025). "The results showed that PLTP, RNASEL, SEMA7A, and TAPBP were upregulated in the whole blood of tuberculosis patients, while NEDD4 and THBS1 were downregulated." (PMID 40182927, 2025).
infection (110 papers, 2006 to 2026). The state of being infected such as from the introduction of a foreign agent such as serum, vaccine, antigenic substance or organism. "Results show that several rare pathogenic/likely pathogenic genomic variants in genes CFTR, MASP2, MEFV, TNFRSF13B, and RNASEL likely contribute to the severe infection outcomes in our patient cohort." (PMID 39062917, 2024). "Moreover, RNAseL functions within a network of innate immune proteins that are associated with cytoskeleton components to serve as a barrier to pathogen infection." (PMID 36982971, 2023). "An increased susceptibility of prostate epithelia cells to infection with RNA-viruses as a result of the impaired function of RNaseL, resulting in proliferative inflammatory atrophy (PIA), could be an intriguing scenario." (PMID 19835577, 2009). "SGs formed during RSV cbVG-high infection even in RNAseL KO cells, and the structure of these granules was unchanged between cell lines, demonstrating that RSV-dependent SGs are not RLBs." (PMID 37983241, 2023). "Expression of either TRS1 or IRS1 prevents activation of the OAS/RNaseL pathway after VACV∆E3L infection." (PMID 35890034, 2022). "The 2′-5′-oligoadenylate synthases (OAS1-3, OASL) were 1.6–7-fold induced upon infection to produce 2′-5′-adenylic acid as second messenger and activator of RNaseL for viral RNA degradation." (PMID 34777295, 2021). "TG also increased the basal expression of the RIG-I signalling-associated genes (RIG-I, IFNB and RNASEL) in NHBE cells, but during infection, the RIG-I-associated gene induction, relative to the infected DMSO control, was noticeably attenuated." (PMID 33546185, 2021). "It is also known as RNaseL-inhibitor and exerts selective control over the stability of mitochondrial mRNAs during interferon-alpha responses to infection." (PMID 33023155, 2020). "Another study conducted on Jamaican fruit bats (Artibeus jamaicensis) also found an increased RNASEL level in the spleen following infection with Tacaribe virus, indicating that RNASEL induction in bats can be observed in vivo." (PMID 33363045, 2020). "Again, comparable to what was previously observed in cell culture, there was a partial phenotypic reversion of CpG- and UpA-high mutants in RNAseL k/o cells (21–29% infection frequencies, and ∼2-fold increases in fluorescent intensities compared to A549 cells." (PMID 31276592, 2019). "Infections in the RNAseL k/o cells were again largely confined to perinuclear regions of the cytoplasm, while E7 RNA FISH signals developed throughout the cytoplasm between the 2 and 6 h time points in the ZAP and OAS3 k/o cells." (PMID 31276592, 2019). "However, histological analysis revealed that RNaseL specifically protected the brain stem from sustained infection and prevented the spread of virus to microglia/macrophages located in spinal cord grey matter." (PMID 38140641, 2023). "In addition to rescuing VACV∆E3L replication, HCMV blocked eIF2α phosphorylation, OAS/RNaseL activation, and the shutoff of protein synthesis that are caused by VACV∆E3L infection." (PMID 35890034, 2022). "Structural analysis of goose OASL suggests it may inhibit infection through both RNaseL-dependent RNA degradation pathway and also RNase L-independent (RIG-I signaling) pathways." (PMID 33276587, 2020). "On the other hand, PRRSV could inhibit IFN-mediated JAK-STAT signaling pathways to interrupt ISG transcription; for example, ISG15, ISG56, CCL2, MX1, OAS2, and RNaseL of PAMs were significantly downregulated after infection with the PRRSV strain VR2385." (PMID 27182980, 2016). "Alternatively, fully spliced mRNAs might be more rapidly degraded after infection, possibly by interferon-mediated induction of RNaseL or off-target binding of viral protein Rev might mediate export of incompletely spliced cellular transcripts." (PMID 26377088, 2015).
infection (continued). "Common genetic variants of genes functionally linked to inflammation and immunity such as COX-2, RNASEL and TLR4 have been associated with prostate cancer risk suggesting that infection and host response to infection may be involved in its development." (PMID 25106851, 2014). "Since none of our samples were positive for XMRV or related MLVs, an association between RNASEL mutation and infection with these viruses could not be investigated." (PMID 23305518, 2013). "Distinct from PKR and RNaseL, the Ifit2 member of the Ifit group of ISGs exerts potent anti-viral activity in the CNS following MHV-A59 infection." (PMID 38140641, 2023). "Moreover, the RNA degradation pattern produced by the expression of RNase L system was identical to the one observed after rTGEV-Δ7 infection, strongly suggesting that RNaseL is the main nuclease involved in the increased RNA degradation after rTGEV-Δ7 infection." (PMID 21695242, 2011). "We suggest that in the early stages of cell culture infection, before viral proteins are in sufficient quantity, the innate immune pathways are active and control infection (RIG-I, PKR, ADAR1, RNaseL, etc.)." (PMID 20502631, 2010). "Additionally, we assessed the activation of three dsRNA-induced pathways, interferon (IFN) production and signaling, oligoadenylate synthetase-ribonuclease L (OAS/RNase L), and protein kinase R (PKR), following infection with each virus." (PMID 41369222, 2026). "Nevertheless, although IFNα/β induction by poly I:C or direct exogenous IFNα/β treatment induced elevated Oas mRNAs in astrocytes, oligodendrocytes, and neurons, RNaseL was not activated by infection." (PMID 38140641, 2023). "Moreover, many genes exhibited different levels of expression of the various isoforms under infection with one PRRSV strain vs. the other (PARP14, SOCS1, IFIT1, MX1, IFOTM1, RNASEL, PIKSCD and TLR3)." (PMID 24643046, 2014). "Nevertheless, infection with HIV-1 did not affect RNaseL expression in these cells." (PMID 37209263, 2023). "In diabetic skin, even in the absence of infection, the antiviral enzymes 2′-5′-oligoadenylate synthetase (OAS) and ribonuclease L (RNase L) demonstrate abnormally heightened activity." (PMID 41457140, 2025). "Regardless of dexamethasone treatment or time post-infection, expression of ISGs of the OAS family, specifically OAS2, OAS3 and OASL, and its downstream RNaseL, were highly upregulated." (PMID 31635289, 2019). "IRF2, RNASEL and SP100 are all upregulated in the CD4 cells of vervet monkey but not of macaques one day post infection." (PMID 31765391, 2019).
tumor (45 papers, 2005 to 2026). "Mutation of RNASEL can lead to dysfunction of Ribonuclease L in regulating single-stranded RNA cleavage, cellular viral defense, and tumor suppressor activities, such as stress-mediated apoptosis and regulation of protein synthesis." (PMID 29088852, 2017). "Genetic association of Hereditary Prostate Cancer 1 (HPC1) to RNASEL expands the role of RNase L to include tumor suppression." (PMID 28257035, 2017). "Since deleterious germline mutations were identified in RNASEL, growing evidence has been reported for the causal quality of the potential tumour suppressor gene." (PMID 15714208, 2005). "Tumor suppressive activities, including antiproliferative and proapoptotic functions, were quickly ascribed and, in 2002, a genetic association was made when RNASEL was identified as the hereditary prostate cancer 1 (HPC1) locus on chromosome 1q25." (PMID 26760998, 2016). "Moreover, we were unable to confirm the correlation between XMRV infection and PCa, higher tumor grade or RNASEL R462Q mutation." (PMID 21447170, 2011). "Serine/threonine–protein phosphatase was identified as a potential growth promoter and therapeutic target, while acid phosphatase, prostate, and ribonuclease L were identified as tumor suppressors." (PMID 40839607, 2025). "RNASEL/RNase-L regulate critical cellular functions including host antiviral response, apoptosis, and tumor-suppressive activity; thus, their expression must be tightly regulated." (PMID 36286041, 2022). "The RNASEL gene has been proposed as a putative tumor suppressor gene located in this region by the positional cloning technique and by the candidate gene approach." (PMID 35655265, 2022). "We found variants in the five genes APC, BRCA1, RET, RNASEL, and STK11 that were linked to autosomal dominant forms of cancer or neoplasm as well as four complex risk variants in ELAC2, MSR1, AIP, and SDHB." (PMID 25333069, 2014). "Due to the tumor suppressor activities of RNASEL it is suggested that RNase L directly or indirectly suppress one or more steps in the prostate tumorigenesis or metastasis formation." (PMID 18575592, 2008). "RNASEL is an endoribonuclease that functions as a tumor suppressor." (PMID 40839607, 2025). "Because of apoptotic properties, RNASEL has been proposed as a tumor-suppressor molecule." (PMID 35565367, 2022). "However, a critical question is whether utilization of RNaseL defective tumor cells to generate xenograft derived cell lines might allow for the evolution of retroviruses that ordinarily cannot escape cellular immune defences." (PMID 23537062, 2013). "Our study found decreased RNASEL expression in FMC cats, indicating that its reduced tumor-suppressing activity contributes to tumor growth and metastasis." (PMID 40839607, 2025). "BIRC5 and HK2 showed higher expression in MYCN amplified cell lines and tumor tissues consistently, whereas GRID2 and RNASEL showed the opposite trends." (PMID 34746127, 2021). "In both TCGA-CESC and FUSCC cohorts, the expression pattern of dsRBPs-related subtypes or genes is consistent: ADAR and DDR subtypes are significantly downregulated in tumor tissues; whereas helicase, OAS RNAseL, PKR and RLR subtypes are significantly overexpressed." (PMID 37735483, 2023). "From the perspectives of tumor tissue and cell lines, we simultaneously found that BIRC5 and HK2 may increase tumor malignancy with MYCN amplification, whereas GRID2 and RNASEL were antagonistic to MYCN amplification." (PMID 34746127, 2021).
tumor (continued). "Interestingly, RNASEL regulates the matrix metalloproteinases activities remodelling the ECM and plays a critical role in cell migration, invasion, tissue metastasis, and impact tumor progression." (PMID 39199663, 2024). "As a result, in the initial stages of anti-androgen drug resistance there is decreased inflammatory response but down regulation of tumor suppressor targets of miR-146a, BCORL1 and RNASEL, which may not be detected in fully developed CRPC." (PMID 24387052, 2014).
cancer (43 papers, 2008 to 2026). A tumor composed of atypical neoplastic, often pleomorphic cells that invade other tissues. "Other genes include GALNT12 which encodes for an enzyme involved in O-linked glycosylation, and RNASEL, a ribonuclease involved in interferon signaling, which have both been implicated as cancer risk genes in population studies." (PMID 39844333, 2025). "These analyses uncovered a strong link between the regulation of RORA and RNASEL, both of which are associated with the immune system response and naive T cell states (they also harbor polymorphisms associated with elevated cancer risk and mortality)." (PMID 36424644, 2022). "An association with RNaseL allelic variation and the risk of human papilloma virus-driven cancers of the cervix and head was demonstrated." (PMID 35505346, 2022). "MiRNA-146a has 224 potential mRNA binding targets on the cancer susceptibility gene RNASEL (Ribonuclease L)." (PMID 34946878, 2021). "Mutations in RNASEL have also been linked to risk other types of cancer, including head and neck, uterine, cervix, breast, pancreatic and hereditary non-polyposis colorectal cancer." (PMID 26517238, 2015). "Ribonuclease L (RNase L) is a metal-ion–independent endoribonuclease associated with antiviral and antibacterial defense, cancer and lifespan." (PMID 24500209, 2014). "Studies from our group and others found that loss-of-function mutations in RNASEL potentially contributed to cancer development by dysregulating apoptosis of cancer cells." (PMID 24371271, 2014). "Ribonuclease L (RNase L) is a well-studied endoribonuclease associated with lifespan, cancer, antibacterial defense and antiviral defense." (PMID 24500209, 2014). "It has been recently determined that RNASEL gene variants D541E, R462Q and I97L are relevant mutations in the prognosis of the cancer." (PMID 24046815, 2013). "Other polymorphisms in the RNASEL gene have been associated with an increased risk of such cancers as prostate, head and neck, uterine cervix and breast; however, this is the first report to our knowledge of an association of rs672527 with cancer." (PMID 23057767, 2012). "The hypothesis has been corroborated by the specific location of the RNASEL gene at the chromosome region 1q25, specifically susceptible to rearrangement in some cancer types." (PMID 35565367, 2022). "Interestingly, one of them, rs486907, causes an amino acid change (R/Q) at position 462 of RNaseL which produces a lower RNaseL activity leading to increased cancer risk." (PMID 28704535, 2017). "MiR-146a has 224 potential mRNA binding targets, including the cancer susceptibility gene RNASEL." (PMID 24699816, 2014). "While RNASEL may be a more general marker of cancer risk, it is possible that RNASEL variants could also impact viral susceptibility, thus increasing the risk of developing a persistent infection with potentially oncogenic viruses such as human papillomavirus (HPV)." (PMID 24699816, 2014). "RNase L gene (RNASEL) plays a role in cancer prevention by degrading RNA, determining cellular stress response and apoptosis." (PMID 37021836, 2023). "RNaseL is also involved in RNA metabolism, autophagy, cell proliferation, cell differentiation and cancer." (PMID 37209263, 2023). "It is likely that distinct effects of Oas-RNaseL activation within the cells of the epithelium and immune system add complexity to the role of this pathway in cancer." (PMID 35505346, 2022). "In our study, the Poly(A) deadenylase and RNASEL were determined in PC tissue, adjacent surgically healthy tissue, and in corresponding healthy counterparts, at least 2 cm from carcinoma." (PMID 35565367, 2022). "Genetic studies have also suggested the possible involvement of the RNase L gene (RNASEL) on chromosome 1q25.3 in several types of cancer." (PMID 26517238, 2015).
cancer (continued). "Genetic variations in RNASEL have been identified in cancers of head and neck, uterus, cervix and breast." (PMID 24371271, 2014). "RNase L: Ribonuclease L (RNASEL) is a key enzyme in the interferon induced antiviral and anti-proliferate pathway and is implicated in the onset and development of viral induced cancers." (PMID 35056738, 2022). "Activation of RNaseL may occur naturally in cancers, hypothesized to be driven by the recognition of double-stranded RNA species by OAS proteins produced from viral sequences integrated in the genome." (PMID 35505346, 2022). "The possible reason why RNASEL expression was highly negatively correlated in carcinoma tissue to its normal counterpart may be found in the immune-suppressive properties of RNASEL." (PMID 35565367, 2022). "Due to its role in the antiviral machinery, a correlation between RNaseL dysregulation and virally induced cancers was hypothesized." (PMID 34809722, 2021). "There is some evidence that RNaseL may be involved in the etiology and progression of cancer." (PMID 35505346, 2022). "Besides, it has been suggested that RNaseL is a key factor in the host immunity against cancer." (PMID 34809722, 2021). "Attention has focused on RNaseL, the down-stream effector of the OAS proteins, activation of which predicted the outcomes in virally induced cancers." (PMID 35505346, 2022).
genetic disease (1 paper, 2016). "We focused our analysis on two apparent high impact mutations in genes known to be related to human genetic disease, ribonuclease L (RNASEL) in animal ON12033 (chr01: 184268143) and BChE in animal ON22186 (chr03:69751554)." (PMID 26935327, 2016).
RNASEL also shares sentences with these, for which no sentence is quoted: Dengue virus infection (6 papers); influenza (6); ovarian carcinoma (4); systemic lupus erythematosus (4); ZIKV infection (4); chronic fatigue syndrome (3); diabetes (3); Flavivirus Infections (3); Autoimmunity (2); bacterial infection (2); bladder cancer (2); fibrosarcoma (2); head and neck squamous cell carcinoma (2); inflammatory bowel disease (2); metabolic syndrome (2); multiple myeloma (2); reovirus infection (2); adenocarcinoma (1); Alzheimer disease (1); atherosclerosis (1); brain infarction (1); breast tumor (1); cardiovascular disease (1); central obesity (1); chronic myelogenous leukemia (1); colitis (1); colorectal cancer (1); colorectal tumors (1); dermatomyositis (1); esophageal cancer (1).
A further 24 diseases each share a sentence with RNASEL in 1 paper.